MTOR (mechanistic target of rapamycin kinase)
Diseases named in the same sentence as MTOR in open-access papers (continued):
Sharing a sentence is not in itself a finding about the gene and the disease.
cancer (continued). "Genetic aberrations of the pathway components such as PI3K, mTOR, Akt, rapamycin-insensitive companion of mammalian target of rapamycin (RICTOR) and phosphatase and tension homologue deleted on chromosome 10 (PTEN) have been reported in different cancer types." (PMID 34203293, 2021). "Mechanistically, CPT inactivates neddylation pathway, which induce the expression of p-IκBα to modulate AMPK/mTOR/ULK1 pathway to trigger pro-survival autophagy, whereas targeting this pathway blocks the autophagic response and thus sensitizes cancer cells to CPT-induced apoptosis." (PMID 33898327, 2021). "The EGFR has been demonstrated to show a negative correlation with DEPTOR and activated mTOR phosphorylation in human cancers." (PMID 34540820, 2021). "Prospectively, RPPA analysis of key EV (phospho-)proteins such as those involved in the EGFR, mechanistic target of rapamycin (mTOR) and vascular endothelial growth factor receptor (VEGFR) pathways, allow cancer- and patient-specific adoption of treatment strategies." (PMID 34155195, 2021). "Exploiting the genetic screening possible in C. elegans might provide further insight how mTOR influences phenotype and disease progression with VHL, and potentially reveal novel concepts to treat VHL-driven cancer." (PMID 34290272, 2021). "We did not address the analysis of the mTOR pathway in cancer cells, in particular in dormant cancer cells, as it is a separate theoretical study and beyond the scope of this study." (PMID 34832087, 2021). "Repurposing of the antifungal agent ICZ for cancer has been based on the identification of several potential cancer targets, including the Hedgehog and the mTOR pathways, but not on its action on proteins of the OSBP family." (PMID 34429859, 2021). "In this regard, a recent report indicated that a prolonged TGF-β exposure promoted stable EMT in mammary epithelial and carcinoma cells, by triggering the mTOR pathway; this stable EMT phenotype contributed to controlling cancer cell stemness drug resistance of breast cancer cells." (PMID 33499083, 2021). "The mTOR-mediated inflammatory response also promotes immune cells recruitment to TME by inflammatory mediators, resulting in exerting the anti-tumor functions or augments tumor growth, progression, and metastatic capacities of cancer cells." (PMID 35250965, 2021). "As a prospective cancer treatment target, suppression of PI3K/AKT/mTOR cascade could trigger apoptosis." (PMID 34821587, 2021). "To date, very few studies have been carried out to explore the significance of racial disparity with abnormal mTOR and ERK-1/2 kinase signaling pathways, which may contribute to the development of aggressive human cancers." (PMID 33996789, 2021). "In both cases, we observed a robust pattern of transcriptional repression leading to the inhibition of relevant cancer-related pathways like ECM receptor interaction, focal adhesion, mTOR signaling, VEGF signaling, ERBB signaling, TGFβ signaling or WNT signalling." (PMID 34488783, 2021). "In line with mTOR inhibition, ULK1 is dephosphorylated on Ser757, and autophagy is consequently upregulated, stabilizing the diapause of mESCs, as well as the dormancy of cancer cells." (PMID 34832087, 2021). "Although mTOR and ERK-1/2 signaling pathways have been well-studied in several human cancers, their association with racial disparity has never been explored." (PMID 33996789, 2021). "In this review, we describe that these polyphenols can alter the function of multiple molecules effective in PI3K signaling, such as Akt, mTOR, PTEN, and PDK-1, through different mechanisms, avoiding cancer progression, drug resistance, angiogenesis, and metastasis." (PMID 34744708, 2021).
cancer (continued). "This has important implications for PI3K-active cancer, where the inhibition of PI3K/mTOR signalling could be severely compromised if a positively-interacting pathway is allowed to remain active." (PMID 34203293, 2021). "Furthermore, enrichment analysis suggested that Kindlins were primarily correlated with the PI3K-Akt signaling pathway, pathways in cancer, HIF-1 signaling pathway, insulin signaling pathway and mTOR signaling pathway." (PMID 33934696, 2021). "During cancer development, AMPK/mTOR pathway becomes dysregulated." (PMID 35070947, 2021). "Moreover, several important pathways such as Wnt, mTOR, MAPK signaling, and miRNA in cancer were significantly enriched in KEGG pathway enrichment analysis." (PMID 34692473, 2021). "Additionally, KEGG pathway enrichment included pathways in cancer, HIF-1 signaling pathway, insulin signaling pathway and mTOR signaling pathway." (PMID 33934696, 2021). "The results showed that these five genes, especially ADORA1, could activate EMT, Hormone ER, PI3K/AKT, RAS/MAPK, TSC/mTOR pathways, and inhibit RTK, Hormone AR, DNA Damage Response, Cell Cycle, Apoptosis pathways to exert regulatory effects in cancer process." (PMID 34093805, 2021). "In contrast to the first and second generations of ALK inhibitors, treatment resistance in the case of lorlatinib is not driven by ALK (acquired) point mutations but is instead driven by the pathway evasion strategies of the cancer cells, namely through the PI3K-Akt-mTOR and the RAS/MAPK pathways." (PMID 34575503, 2021). "﻿In response to anti-cancer drugs, WM_Score highly negatively correlated (drug sensitive) with drugs which targeted oncogenic related pathways, such as MAPK, EGFR, and mTOR signaling pathways, positively correlated (drug resistance) with drugs which targeted in apoptosis and cell cycle." (PMID 33557837, 2021). "The PI3K/AKT/mTOR pathway facilitates the combination of HK2 and the outer mitochondrial membrane, which maintains a high metabolic rate, stemness, and promotes proliferation, invasion, metastasis, and chemoresistance of cancer." (PMID 34540667, 2021). "We conclude that MAPK6 can promote cancer by activating AKT and that targeting MAPK6, either alone or in combination with mTOR kinase blockade, may provide effective therapeutic approaches for cancer." (PMID 34767444, 2021). "AKT activation could trigger the Warburg effect in cancer cells and PI3K-Akt-mTOR pathway is a key intracellular signaling pathway in regulating metabolic checkpoints." (PMID 33588886, 2021). "Other studies have shown that ARRB1 regulates several cancer-related cellular processes via diverse signal transduction pathways, including the Ras/Raf/MEK/ERK family, β-catenin/TCF4 signalling, Akt/GSK3β signalling, mTOR signalling and NF-κB signalling." (PMID 34380537, 2021). "Likewise, DADS treatment suppresses cancer progression by facilitating DNA damage 120 and inhibiting PI3K/AKT/mTOR 142, 143 and NF-кB pathways." (PMID 33390834, 2021). "In order to explore the molecular mechanism via which CDC37L1 inhibited GC cell proliferation and migration, we detected the expression of several cancer signaling pathway factors, such as CDK4, CDK6, Cyclin D1, FAK, PI3K-P110 and mTOR through western blot assays." (PMID 33976724, 2021). "Signal pathways such as AMP-activated protein kinase (AMPK), mammalian target of rapamycin (mTOR), and sirtuin 1 (SIRT1) and autophagy-related pathways may also bridge T2D and CRC and participate in cancer progression." (PMID 34434893, 2021). "Furthermore, DHA induced apoptosis in cancer cells by stimulating AMPK, PI3K‐Akt, and mTOR signaling." (PMID 34646077, 2021).
cancer (continued). "In addition to the C‐MET/STAT3 cascade, both AKT/mTOR and MAPK pathways can mediate the aberrant growth and apoptosis resistance of cancer cells." (PMID 34586726, 2021). "Meanwhile, in in vitro studies, TQ has shown the ability to inhibit cancer staging such as migration, proliferation, and invasion or apoptosis induction by repressing the activation of vital pathways, such as JAK/STAT and PI3K/AKT/mTOR." (PMID 33923474, 2021). "New combination strategies may improve patient tolerance to PI3K/mTOR, such as inhibiting PI3K/mTOR pathway only when cancer cells experience radiation-induced stress, which may offer short-term synergistic effects combined with radiotherapy." (PMID 34065268, 2021). "Additionally, transcripts of genes related to pathways regulating cell survival and migration such as mTOR, c-Myc, COX 2, NF-κB (p65), bcr/abl, WT1, TGF-β1 and MMP-935,36 were also found to be downregulated, excepting PTEN in cancer cells exposed to CMRP." (PMID 33436696, 2021). "Blocking these pathways, alone or in combination with PI3K/Akt/mTOR inhibition, may have synergistic benefit in overcoming PI3K-driven cancer." (PMID 34203293, 2021). "Moreover, several common cancer-related pathways, including the WNT, TGF-β, mTOR, MAPK, JAK-STAT, and ERBB pathways, were also activated." (PMID 34671200, 2021). "Metformin has been shown to directly induce antitumor effects by inhibiting the PI3K-Akt/mTOR and Ras-MAPK signaling pathways critical for cancer progression and indirectly by systemically reducing glucose and insulin metabolism to attenuate cancer cell growth." (PMID 34881181, 2021). "Although mTOR is a well-known inhibitor of autophagy-dependent survival in physiological conditions, many recent studies have revealed that autophagy becomes hyper-active in KRAS mutant cancer cells." (PMID 33925206, 2021). "In this case-control study with a large proportion of Black women, we compared several body fatness measurements between cases with p-mTOR overexpressed tumors or p-mTOR negative/low tumors with non-cancer controls." (PMID 34330319, 2021). "Other known cancer pathways are also altered by UMGs and include Notch, HIF-1, and mTOR." (PMID 34620211, 2021). "Hence, mTOR inhibitors represent a therapeutic opportunity to promote antitumor CD8 responses and to boost the efficacy of different modalities of cancer immunotherapy." (PMID 33802831, 2021). "Moreover, it targets the AMP-activated protein kinase alpha 2 (AMPKα2) for ubiquitination and degradation, activating the mammalian target of rapamycin (mTOR)–hypoxia-inducible factor 1-alpha (HIF-1α) axis and promoting cancer progression." (PMID 34199813, 2021). "Moreover, CDKN2B-AS1 interacts with signaling pathways in cancers, such as p38 MAPK, PI3K/AKT, mTOR, ATM-E2F1, and TGF-β19." (PMID 33608495, 2021). "In the meantime, they also found that in vitro knockout of TINCR contributed to significantly decreased levels of cancer cell proliferation, while the overexpression of TINCR was conducive to cancer progression with the involvement of miR-7-5p and PI3K/Akt/mTOR signaling." (PMID 35223868, 2021). "Both mTOR and c-MYC are well-known master regulators of cellular metabolism and have been shown to regulate the TCA cycle and mitochondrial function, thus driving metabolic rewiring in cancer 68-70." (PMID 33754045, 2021). "The role of mTOR and RAS pathways in cancer has been proven in many studies." (PMID 34604242, 2021). "Our findings identified inhibitors of the phosphatidylinositol 3-kinase/AKT/mammalian target of rapamycin (PI3K/Akt/mTOR) signaling pathway, one of the most aberrantly regulated cellular pathways in cancer, as novel candidate drugs to treat NB patients with hypoxic tumors." (PMID 34199959, 2021).
cancer (continued). "The pathways enriched with candidate miRNA–targets were reportedly involved in metastasis, invasion, and cancer progression; these are transcriptional misregulation in cancer, Wnt signaling pathway, mTOR signaling pathway, MAPK signaling pathway, and miRNA in cancer." (PMID 34692473, 2021). "Furthermore, it has been observed in several studies that external factors (growth factors, nutrient intake) can activate Akt and mTOR, thereby bypassing PI3K and thus restarting cancer genesis." (PMID 34500781, 2021). "Naringin and its aglycone naringenin have shown anti-carcinogenic activities through cell signal transduction pathways in cancer (JAK–STAT pathway, PI3-kinase/Akt/mTOR pathway, Notch pathway, NF-κB and cox-2 pathway, Wnt pathway, MAPK-ERK pathway, TGF-β pathway)." (PMID 34220510, 2021). "The PI3K/AKT/mTOR pathway, once activated by IGF-I and other growth factors, leads to a series of signaling cascades that promote cell proliferation, growth, invasion, and metastases of various cancers, including OvCa." (PMID 34440224, 2021). "Stemness is responsible for initiating metastasis and cancer recurrence, and miRNAs are involved in the maintenance of the cancer stem cell via targeting main signaling pathways such as WNT/β-catenin, NOTCH, NF-kB, PI3K/AKT/mTOR, BMI-1, and STAT3." (PMID 34846108, 2021). "With links to mTOR, Akt and cMyc, it comes as no surprise that PIK3CA mutations can influence metabolic programs in a number of cancer types." (PMID 34283054, 2021). "Another compound named 3,3′,4′-trimethylellagic acid (TMEA), a tannin compound isolated from Sanguisorba officinalis L., executed its anti-cancer activity by inducing apoptosis and inhibiting angiogenesis in CRC cells via the apoptotic and VEGF/PI3K/AKT/mTOR pathways." (PMID 34202548, 2021). "Collectively, this study suggested that NSC765598 has a potential for multi-target inhibition of EGFR/iNOS/mTOR/TGFB1/FGFR/MAP2K1 and could serve as a lead compound for developing new therapeutics for cancer treatment." (PMID 33842373, 2021). "Toll-like receptor (TLR) signaling pathway and transcriptional regulation in cancer were enriched in Ven and Ven-PegC treatment, while Janus kinases (JAK), signal transducer and activator of transcription proteins (STAT), mTOR and Interleukin 17 (IL17) were noted to be enriched upon PegC treatment." (PMID 33199836, 2021). "Drugs with targets such as EGFR, ERBB2, MTOR, PARP2, AURKB, MAP2K1 and PLK1 share more similar profiles, which indicates that the inhibition of these targets has specific effects on the in vitro viability and proliferation of cancer cells." (PMID 33795761, 2021). "Neferine induces autophagic cell death in a panel of cancer cells, including apoptosis-defective and -resistant cancer cells or isogenic cancer cells, via Ca2+ mobilization through the activation of ryanodine receptor and ULK1/PERK and AMPK/mTOR signaling cascades." (PMID 34575981, 2021). "Increased Akt activity in the PI3 K/Akt/mTOR pathway (d) was found to be sufficient to induce the Warburg effect in both cancer as well as in nontransformed cells." (PMID 33400855, 2021). "For example, Salmonella may induce cancer cell apoptosis through nutrient competition, release of bacterial toxins, and down-regulation of the AKT/mTOR pathway." (PMID 35003007, 2021).
cancer (continued). "Importantly, FAK is a protein tyrosine kinase that regulates cancer cell adhesion, migration, and metastasis by activating signal transducers, including PI3K, Akt, mTOR, and RAS." (PMID 33920031, 2021). "HDW can suppress the activation of the AKT/mTOR pathway in HCC cells, which may bring new light for the treatment of this kind of malignant tumor, but its exact mechanism still needs to be further explored." (PMID 34527062, 2021). "It is known that in different human cancers Btg2 (human ortholog of the mouse gene Tis21) inhibits the processes of cell proliferation, survival and metastasis by suppressing the PI3K/AKT/mTOR pathway, since the Btg2 protein acts as a negative regulator of AKT in both tumor cells and normal ones." (PMID 34395258, 2021). "Indeed, metformin alters the energetic activity of cancer cells by downregulating the expression of HIF-1α and mTOR, by limiting the activity of the protumor isoform HK2 and by inhibiting complex 1 of the electron transport chain." (PMID 34885023, 2021). "Specifically, mammalian target of rapamycin inhibitors are approved by the US Food and Drug Administration (FDA) for cancer therapy, and the combination of mTOR inhibitors with TMZ during radiotherapy to trigger autophagic cell death is thought to be a promising treatment approach." (PMID 32577848, 2021). "Accordingly, mTOR inhibitors have been thoroughly explored in cancer therapy but have failed to provide long-lasting anticancer benefits." (PMID 33802831, 2021). "We demonstrated that mTOR and TrxR inhibitors cooperated to induce cell death by triggering oxidative stress, which led to activation of autophagy, endoplasmic reticulum (ER) stress and c-Jun N-terminal Kinase (JNK) signaling pathway in cancer cells." (PMID 33754064, 2021). "Besides, the regulatory pathways that are widely accepted to regulate and maintain CSCs in cancers, including the AKT and mTOR signals, were suppressed by the treatment of ovalitenone." (PMID 33530617, 2021). "Given the significant role that the pathway plays in regulating cell survival, proliferation, and metabolism, it is not surprising to see PI3K/Akt/mTOR signaling deregulated in many cancers." (PMID 34221985, 2021). "The Akt/mTOR pathway is an important negative pathway in the activation of autophagy; it is also involved in regulating cancer cell proliferation, migration, cell cycle, and apoptosis." (PMID 35096055, 2021). "The mTOR and ERK-1/2 signaling pathways are one of the well-known oncogenic signaling mechanisms that regulate diverse molecular and phenotypic aspects of normal as well as cancer cells in response to different external or internal stimuli." (PMID 33996789, 2021). "Targeting glucose metabolism by a direct glycolysis pathway inhibitor or indirect inhibitor through other pathways, such as the mTOR or AMPK pathways, with ISR activators may be a useful direction for the further development of cancer therapy." (PMID 34572286, 2021). "We further demonstrate that increased autophagy upon mTOR inhibitors and auranofin combination treatment promoted cancer cell death rather than cell survival." (PMID 33754064, 2021). "Moreover, RABL6A is a potent oncoprotein that controls many druggable cancer targets besides CDK4/6 and MEK, including Myc, PP2A-Akt-mTOR, and receptor tyrosine kinase pathways like VEGFR and EGFR." (PMID 33456709, 2021). "However, how cancer cells in GBM alter glycolytic metabolism and how inhibition of PI3K/AKT/mTOR alters glycolytic gene expression remained unclear." (PMID 34831287, 2021). "In addition, NORAD has interactions with cancer-related pathways such as STAT, TGF-β, Akt/mTOR, and PI3K/AKT pathway." (PMID 34485302, 2021). "The mTOR kinase is a core downstream molecule of PI3K/Akt to modulate cellular growth, metabolism, and migration, and its signaling pathway is frequently dysregulated in a variety of cancers." (PMID 34659408, 2021).